IL6 (interleukin 6)
Diseases named in the same sentence as IL6 in open-access papers (continued):
Sharing a sentence is not in itself a finding about the gene and the disease.
trigeminal neuralgia (6 papers, 2021 to 2025). Trigeminal neuralgia is a nerve disorder that causes a stabbing or electric-shock-like pain in parts of the face. "Our findings implicated a possibility to cure the trigeminal neuralgia with a noninvasive targeting therapy instead of open-brain surgery in the future as long as we could block the IL-6/Piezo2 pathway." (PMID 33893246, 2021). "In male trigeminal neuralgia models, RvD5 downregulates IL-6 production specifically in male models of trigeminal neuralgia." (PMID 41246324, 2025). "In addition, certain pro-inflammatory cytokines, like TNF-a, IL-17, and IL-6, were also found to be elevated in the saliva of trigeminal neuralgia patients compared to controls." (PMID 35237471, 2022). "Two studies in trigeminal neuralgia, induced by either IoNC or compression of the trigeminal nerve root, demonstrated significant ipsilateral reduction of the upregulated proinflammatory cytokine IL-6 after BoNT treatment when compared to vehicle saline, in TG and TNC." (PMID 40864053, 2025). "In the present study patients with trigeminal neuralgia showed lower levels of growth factor levels such as Ang-2, bFGF, HGF, SCF, TGF-α, and VEGF and higher cytokine levels of IL-1β, TNF-α, CCL2, IL-17A, IL-6, and CXCL8 in comparison with normal individuals." (PMID 34067581, 2021). "In view of recent reports of significant up-regulation of TNF-α and IL-6 in trigeminal ganglion in rodent models of trigeminal neuralgia, it would be interesting to study the trigeminal nociception in PD mice challenged with Aa EVs." (PMID 37871107, 2023).
urothelial carcinoma (6 papers, 2005 to 2025). A malignant neoplasm derived from the transitional epithelium of the urinary tract (urinary bladder, ureter, urethra, or renal pelvis). "It is suggested that alteration of the autocrine IL-6 response to BCG via pharmacological manipulation of the estrogen milieu may have a therapeutic value for urothelial carcinoma, however, the underlying mechanisms remain unclear." (PMID 27092883, 2016).
uterine cancer (6 papers, 2011 to 2024). Primary or metastatic malignant neoplasm involving the uterine corpus and/or the cervix. "Therefore, uterine cancer survivors may face an increased risk of inflammation-related pain due to the secretion of pro-inflammatory biomarkers, such as interleukin (IL)-6, by uterine tumors." (PMID 38662054, 2024). "The literature also confirms the participation of IL-6 as an inflammatory factor in the proliferation of cancerous cells in some cancers, including metastasis of uterine cancer." (PMID 36834426, 2023). "Furthermore, bladder, cervical, endometrioid, and uterine cancers, displayed IL6 upregulation and both IL6R and IL6ST downregulation." (PMID 34576335, 2021). "Dexmedetomidine administration in patients undergoing uterine cancer surgery did not demonstrate a favorable impact on immunity in terms of perioperative changes of NK cell activity, IL-6, and NLR." (PMID 34868950, 2021). "Furthermore, the IL-6 autocrine loop upregulated expressions of anti-apoptotic genes, such as Bcl-2, Bcl-xL, and XIAP, and drug resistance genes, such as MDR-1 and GSTpi, accompanied by the activation of the Ras/MEK/ERK and PI3K/Akt pathways in uterine cancer cells." (PMID 34226586, 2021).
acute-on-chronic liver failure (5 papers, 2020 to 2025). Acute-on-chronic liver failure (ACLF) is an extreme condition during the natural history of chronic HBV infection, with a relatively high short-term mortality. "Furthermore, the levels of pro-inflammatory cytokines such as IL-6 and TNF were reduced in patients with acute-on-chronic liver failure." (PMID 41464873, 2025).
aggressive periodontitis (5 papers, 2015 to 2025). "In studies of aggressive periodontitis (PDag) and chronic PD (CPD), 6 proinflammatory mediators (IL-1β, IL-6, IFN-γ, TNF-α, IL-17, and IL-12) and 2 common anti-inflammatory mediators (TGF-β and IL-4) were involved." (PMID 26339136, 2015).
alexithymia (5 papers, 2018 to 2025). An agnosia that is a deficiency in understanding, processing, or describing emotions. "This relationship is further supported by biological evidence linking alexithymia to increased activation of the sympathetic nervous system and the hypothalamic-pituitary-adrenal axis, as well as elevated levels of inflammatory cytokines such as IL-6." (PMID 40682176, 2025). "Similarly, with specific regard to alexithymia, recent studies highlighted a pathogenetic correlation with specific inflammatory markers such as TNF-α and IL-6 exists." (PMID 36140234, 2022).
allergic conjunctivitis (5 papers, 2011 to 2026). "IL-6 can induce the proliferation of mast cells, thereby contributing to the immunopathology associated with mast cell-mediated diseases such as allergic conjunctivitis." (PMID 38541674, 2024). "It has been demonstrated that IL-6 can increase the proliferation of mast cells, thereby contributing to the immunopathology associated with mast cell-mediated diseases such as allergic conjunctivitis." (PMID 38541674, 2024). "A study reported increases in IL-1β, IL-2, IL-5, IL-6, IL-12, IL-13, in seasonal allergic conjunctivitis (SAC), vernal keratoconjunctivitis (VKC) and atopic keratoconjunctivitis (AKC), while IL-4, IFN-γ and IL-10 levels were increased in SAC and VKC compared to controls." (PMID 21298010, 2011). "Further studies isolating CD4+TLR4+ cells from blood samples from allergic conjunctivitis patients and stimulating them with Der p are needed to determine if CD4+TLR4+ cells have a role in the induction of the IL-6 pro-inflammatory microenvironment and the inhibition of Treg cells." (PMID 33114004, 2020). "In sum, the activation of CD4+TLR4+T cells by the antigen and TLR induces an inflammatory microenvironment characterized by TNF-α, IL-6, and IL-4, which favors a lack of immune regulation in perennial allergic conjunctivitis." (PMID 33114004, 2020).
ameloblastoma (5 papers, 2017 to 2024). The most common odontogenic tumor, arising from the epithelial component of the embryonic tooth and usually affecting the molar-ramus region of the mandible or maxilla. "IL-6 is a cytokine with osteolytic activity and has been implicated in the growth and expansion of ameloblastoma by promoting tumor growth and modifying bone remodeling." (PMID 35243014, 2022). "Several studies reported that some cytokines were secreted from ameloblastoma cells, including IL-1α, IL-1β, IL-6, and TNF-α." (PMID 35243014, 2022). "We previously reported that the productions of IL-6 and IL-8 were induced in stromal fibroblasts stimulated with AM-3 ameloblastoma-derived IL-1α." (PMID 35243014, 2022). "In conclusion, ameloblastoma cells stimulated osteoblasts to produce IL-6, MCP-1, and RANTES, which can promote tumor growth and modify the bone remodeling process by inducing osteoclastogenesis." (PMID 35243014, 2022). "Our group recently determined that interactions between ameloblastoma tumor cells and stromal fibroblasts are often conveyed by various cytokines including interleukin (IL)‐1α, IL‐6, and IL‐8, which create a microenvironment favorable to tumor invasion." (PMID 29226086, 2017). "Findings on this study showed that MC3T3-E1 osteoblast cells secreted IL-6, MCP-1, and RANTES in response to the intercellular communication between ameloblastoma cells and osteoblasts." (PMID 35243014, 2022). "This study found that MC3T3-E1 osteoblast cells produced IL-6, MCP-1, and RANTES in the presence of ameloblastoma CM." (PMID 35243014, 2022). "Other group reported that TNF‐α induced the expression IL‐6 and MMP‐9 from ameloblastoma cells." (PMID 29226086, 2017). "Besides that, the MC3T3-E1 CM of the unstimulated condition itself showed a stimulatory effect on proliferation and migration capability of AM-3 ameloblastoma cells, whereas IL-6, MCP-1 and RANTES were not secreted in the unstimulated MC3T3-E1 CM." (PMID 35243014, 2022). "It has been reported that activation of the Wnt/β-catenin pathway and IL-6/STAT3 signaling by LRP5 could promote neoplasm cells to acquire chemoresistance and the cancer stem cell phenotype, which should be considered when establishing chemotherapeutic approaches against ameloblastomas." (PMID 37628576, 2023).
ANCA-associated vasculitis (5 papers, 2014 to 2024). "Yokoseki also reported increased levels of IL-6, C-X-C motif ligand (CXCL)-8, and CXCL-10/IFN-γ inducible protein (IP)-10 in cerebrospinal fluid of HP with ANCA-associated vasculitis or IgG4-RD." (PMID 38988571, 2024).
asphyxia (5 papers, 2013 to 2021). A state of general hypoxia and hypercapnia (abnormally elevated carbon dioxide (CO2) levels in the blood), resulting in acidosis, which affects all tissues in the body. "In anotherstudy, the increase in serum IL6 was associated with poor outcomes or death ininfants with perinatal asphyxia." (PMID 31435616, 2019). "A study on theneurological markers (IL6) in perinatal asphyxia and its relationship withdifferent stages of HIE was performed on 100 asphyxic and 100 healthy neonateswith blood samplings in the first and third days of birth." (PMID 31435616, 2019). "Available studies have indicated that IL6> 41 pg/dLhad sensitivity and specificity of 88.84% and 85.43%, respectively, in the diagnosisof neonatal asphyxia." (PMID 31435616, 2019). "Higher levels of IL6 have beenreported in infants with perinatal asphyxia and hypothermia." (PMID 31435616, 2019). "IL6 serum is useful predictors for the outcomesof HIE and intensity of perinatal asphyxia." (PMID 31435616, 2019). "Thus, FasL and IL-6 alone and together predicted the degree of HIE better than this well-known standard marker of perinatal asphyxia." (PMID 30089504, 2018).
Bell's palsy (5 papers, 2021 to 2025). Partial or complete paralysis of the facial muscles of one side of a person's face. "The measurements of the serum samples from patients with Bell’s palsy showed significantly higher levels of IL-6, IL-8, and TNF-α in patients with Bell’s palsy compared to controls." (PMID 38689877, 2024). "Furthermore, related studies found that patients with Bell’s palsy had elevated concentrations of cytokines in serum samples compared to controls, including IL-1 and IL-6." (PMID 40299566, 2025). "To further elucidate the potential role of inflammatory immune-related proteins in Bell palsy, we constructed a PPI network and screened 31 high-confidence interacting proteins, among which IL-6 showed a high degree of connectivity." (PMID 40299566, 2025). "Elevated cytokines (IL-1, IL-6) and tumour necrosis factor (TNF a) were found in the patients with Bell's Palsy in comparison to a control group." (PMID 36212732, 2022). "Evaluation of patients with Bell’s palsy has shown the increase in serum levels of IL1, IL6, and TNF-alpha (Tumor Necrozing Factor) compared to healthy individuals, representing the activities of the cell-mediated immune system’s operative factors." (PMID 35474925, 2021). "It was already well established that IL6, IL8 and TNF-alpha levels were significantly higher in Bell’s palsy, but serum levels of these cytokines do not help to determine the prognosis in Bell’s palsy." (PMID 35474925, 2021).
bronchiolitis obliterans (5 papers, 2016 to 2025). "The expression of Ccl3, Ccl4, and Il6 were all down-regulated in macrophages exposed to NR58-3.14.3 and are consistent with the down-regulation of Il6 observed in experimental obliterative bronchiolitis following administration of NR58-3.14.3." (PMID 26911327, 2016). "In addition, bronchiolitis obliterans (OB) patients with lung transplant have increased IL-17 and Th17 differentiating cytokines (IL-1β, IL-6, and IL-23) in the BAL fluid compared with the controls." (PMID 33419073, 2021). "Gene expression profiling of human and murine organizing pneumonia lesions showed in part comparable expression levels of pivotal genes, notably of TGFB1/Tgfb1, TIMP1/Timp1, TIMP2/Timp2, COL3A1/Col3a1, CXCL12/Cxcl12, MMP2/Mmp2 and IL6/Il6." (PMID 27282780, 2016). "Our study showed that APN suppressed proinflammatory factors (TNF-α and IL-6) through SIRT1- PINK1 signaling-mediated mitophagy, leading to inhibition of lung IR injury, which might mitigate the subsequent occurrence of acute graft rejection and obliterative bronchiolitis." (PMID 34602075, 2021).
bullous pemphigoid (5 papers, 2013 to 2023). Bullous pemphigoid (BP) is the most common form of autoimmune bullous dermatosis. "On the other hand, IL-6, the hallmark cytokine of bullous pemphigoid (BP) severity, was found to be upregulated in HaCaT cells by vildagliptin." (PMID 36430582, 2022). "For example, high concentrations of IL-6, IL-22 and IL-23 were observed in IL-17+ neutrophils in bullous pemphigoid blister fluid." (PMID 26213975, 2015). "It has already been proven that the levels of some proinflammatory cytokines, such as interleukin (IL)-1a, IL-6 IL-8, IL-17a, TNF-alpha, and IFN-c, were higher in the aqueous humor of eyes with bullous keratopathy and a low density of ECs." (PMID 36968840, 2023). "Despite the fact that the effect of IL-6 on autoantibody production in EBA is not known at the moment, great caution should be taken when considering blocking IL-6 functions in patients with EBA (and possibly other related diseases such as bullous pemphigoid)." (PMID 23956869, 2013).
burning mouth syndrome (5 papers, 2006 to 2021). A condition characterized by a burning or tingling sensation on the lips, tongue, or entire mouth. "Serum interleukin-6 in patients with burning mouth syndrome is decreased and negatively correlated to chronic pain." (PMID 17641729, 2007).
calcinosis (5 papers, 2010 to 2023). Deposition of calcium in the tissues. "Cytokines such as IL-6, IL-1β, TNF-α, IL-1β, and IL-6 were also detected in serum, suggesting the role of activated macrophages in JDM-associated calcinosis." (PMID 32550037, 2020).
campylobacteriosis (5 papers, 2014 to 2021). Infections with bacteria of the genus campylobacter. "The peak levels of IL-8 and IL-6 are consistent with studies on clinical human cases of campylobacteriosis." (PMID 28196097, 2017). "Strikingly, the potent campylobacteriosis ameliorating effects upon carvacrol treatment could also be assessed systemically given that serum concentrations of TNF, IFN-γ, MCP-1 and IL-6 were lower in carvacrol as compared to PLC treated C. jejuni infected mice." (PMID 31921356, 2020).
cerebral small vessel disease (5 papers, 2020 to 2026). Cerebral small vessel disease is the term currently used to pathological processes that affect the brain parenchymal circulation (arterioles, capillaries, and veins). "The IL-6, epinephrine, high-mobility group protein B1, neuropeptide Y, theta oscillations in the hippocampal neurons, and cerebral small vessel disease have been recently implicated in the pathogenesis of PSE." (PMID 36338344, 2022). "A recent systematic review analyzed the role of vascular (e.g. VWF, homocysteine) and systemic (e.g. CRP, IL-6) inflammatory biomarkers in relation to cerebral small vessel disease (SVD) in a non-CKD population." (PMID 35042473, 2022).
chronic liver failure (5 papers, 2013 to 2025). Liver failure that develops slowly and gradually for some time, possibly for years, often as the result of cirrhosis, or malnutrition. "Inflammatory molecules, including cytokines interleukin-1 (IL-1), interleukin-6 (IL-6), and tumor necrosis factor-alpha (TNF-α), are increased in plasma during acute and chronic liver failure in patients and in animals with experimentally induced HE." (PMID 23762040, 2013).
chronic spontaneous urticaria (5 papers, 2015 to 2025). "Therefore, we investigated the clinical relevance of soluble members of IL-6 trans-signaling system in chronic spontaneous urticaria (CSU)." (PMID 26699882, 2015). "Therefore, IL-6 and IFN-gamma have the potential to be valuable biomarkers for disease type and severity in chronic spontaneous urticaria." (PMID 35744079, 2022).
clear cell carcinoma (5 papers, 2012 to 2025). "The JHOC-5 clear cell carcinoma cell line bears the tumor suppressor gene ARID1A (encoding BAF250) and PIK3CA mutations, which cooperate to promote tumor growth through IL-6 overproduction." (PMID 29930760, 2018). "Clear cell carcinoma cells also produce high levels of IL-6 and other TNF network members (our unpublished data)." (PMID 26871292, 2016). "Clear cell carcinomas have been reported to oversecrete IL-6 more than other histologic types." (PMID 39755760, 2025). "MYC is an oncogenic downstream target of KRAS and IL6-JAK-STAT signaling and therefore we correlated the expression of MYC and RASSF10 in primary renal papillary cell carcinoma and clear cell carcinoma." (PMID 32047266, 2020). "Clinically relevant is the fact that the AMPK activator, AICAR, which we show in this study to reduce Nox4 expression and IL-6 and IL-8 production, reduces RCC cell invasion in vitro and in ex vivo RCC cells isolated from a human clear cell carcinoma tumor." (PMID 22303451, 2012).
colonic diseases (5 papers, 2010 to 2025). "IBD is a colon disorder associated with increased levels of proinflammatory cytokines, including tumor necrosis factor-a, interleukin (IL)-1b, IL-2, and IL-6." (PMID 39979878, 2025). "Links to functional immune status and prognosis: In human colonic disease, TLR-4 and IL-6 expression in the tumor microenvironment were associated with adenocarcinoma." (PMID 41465346, 2025).
coronary aneurysm (5 papers, 2012 to 2025). Abnormal balloon- or sac-like dilatation in the wall of coronary vessels. "A cytokine storm including tumor necrosis factor (TNF)-α, IL-6, and granulocyte colony-stimulating factor is evident in patients in whom coronary artery aneurysms are developing." (PMID 30547812, 2018). "While KD involves chronic endothelial activation and a significant risk of coronary aneurysms, MIS-C is characterized by acute elevations in proinflammatory cytokines—such as IL-6, IL-1β, and TNF-α—leading to systemic inflammation and transient cardiac dysfunction." (PMID 40332089, 2025). "Furthermore, interleukin (IL)-6 and tumor necrosis factor-α levels were also significantly higher in KD patients with coronary aneurysm compared to those without coronary aneurysm." (PMID 22577247, 2012). "Also in KD IL-6 is increased in serum, but contrary to VEGF, the increase was not correlated with the development of coronary artery aneurysms and dilatation." (PMID 23379382, 2013).
demyelination (5 papers, 2016 to 2025). "Both ASD and cerebellar demyelination were caused by elevated IL-6." (PMID 40652064, 2025). "Overall, our results suggest that IL-6, IL-10 or TGF-β are not required for TH17 cell induced demyelination and expression of IL-2 by HSV-IL-2 plays an important role in the generation of pathogenic TH17 cells as was reported previously." (PMID 36817487, 2023).
Dry skin (5 papers, 2017 to 2026). Skin characterized by the lack of natural or normal moisture. "In uremic pruritus, it is probably secondary to CKD‐related xerosis, higher skin‐surface pH, and gut microbiota imbalance, with an immune milieu marked by elevated interleukin (IL)‐2, IL‐6, IL‐31, histamine, and altered monocyte subsets." (PMID 40528508, 2025). "This leads to dry skin, activation of immune cells and keratinocytes in the epidermis, and production of proinflammatory cytokines which induce dermal T lymphocytes to produce IL-6 and IL-17 inflammatory cytokines." (PMID 28779153, 2017). "Furthermore, due to the dysfunction of EGFR, the release of cytokines such as IL-6 and TNF-α and the decreased production of cell adhesion factors such as claudin resulted in dry skin." (PMID 32252690, 2020).